ATCAY (ATCAY kinesin light chain interacting caytaxin)
Description:
Functions in the development of neural tissues, particularly the postnatal maturation of the cerebellar cortex. May play a role in neurotransmission through regulation of glutaminase/GLS, an enzyme responsible for the production in neurons of the glutamate neurotransmitter. Alternatively, may regulate the localization of mitochondria within axons and dendrites.
Synonyms: BNIP-H; CLAC
Tractability: PROTAC: UniProt records ubiquitination sites on it; its protein half-life has been measured.
Gene: Protein-coding gene on chromosome 19 (3,879,864 to 3,928,082, forward strand). Ensembl gene ENSG00000167654.
Subcellular location: Cell projection, axon; Cell projection, dendrite; Presynapse; Mitochondrion; Cell projection, growth cone; Cytoplasm
Gene Ontology:
Molecular function: kinesin binding; protein binding
Biological process: negative regulation of L-glutamine biosynthetic process; apoptotic process; mitochondrion distribution; neuron projection development
Cellular component: cytoplasm; mitochondrion; neuron projection; presynapse; axon; dendrite; mitochondrial membrane; synapse; growth cone; neuron projection terminus; perinuclear region of cytoplasm
Genetic constraint (gnomAD): Loss-of-function variants: 22 observed, 43.36 expected, observed/expected ratio (o/e) 0.51, 90% interval 0.36 to 0.73. The upper end of that interval is the gene's LOEUF score, 0.73, which puts it in group 2 of 6, group 1 being the genes least tolerant of losing a copy. Missense variants: 452 observed, 508.18 expected, observed/expected ratio (o/e) 0.89, 90% interval 0.82 to 0.96. Synonymous variants: 216 observed, 206.83 expected, observed/expected ratio (o/e) 1.04, 90% interval 0.93 to 1.17.
Homologues: Orthologues: chimpanzee ATCAY (99% identical), macaque ATCAY (99% identical), dog ATCAY (95% identical), pig ATCAY (95% identical), mouse Atcay (91% identical), rat Atcay (91% identical), guinea pig ATCAY (90% identical), tropical clawed frog atcay (81% identical), zebrafish atcaya (66% identical), zebrafish atcayb (64% identical), Drosophila melanogaster CG11593 (33% identical). Paralogues in human: PRUNE2 (54% identical), BNIP2 (47% identical), BNIPL (36% identical).
Diseases named in the same sentence as ATCAY in open-access papers:
ATCAY is named in the same sentence as 11 diseases in open-access papers, as found by Europe PMC text mining. Sharing a sentence is not in itself a finding about the gene and the disease. The quoted sentences say what the papers report.
Cayman cerebellar ataxia (2 papers, 2008 to 2023). "Pathogenic variants in the ATCAY gene are associated with a rare autosomal recessive disorder called Cayman cerebellar ataxia." (PMID 37752557, 2023).
Dystonia (1 paper, 2011). An abnormally increased muscular tone that causes fixed abnormal postures. "A potentially interesting candidate for the largest FEB/GEFS+ orphan locus is the ATCAY gene, which has been found mutated in human Cayman ataxia and in a form of rat dystonia." (PMID 21858011, 2011).
glioma (1 paper, 2020). A benign or malignant brain and spinal cord tumor that arises from glial cells (astrocytes, oligodendrocytes, ependymal cells). "In addition, the expression levels of four of these genes (ATCAY, CELF3, ELAVL3 and UGT8) were highest in normal brain tissues, and negatively correlated with glioma grades." (PMID 32091665, 2020).
prostate carcinoma (1 paper, 2023). A carcinoma that arises from epithelial cells of the prostate gland. "We validated the expression levels of 5 prognostic genes in the TCGA-PRAD and found that both ATCAY and GLUL were lower expressed in the tumor tissues than normal prostate tissues, while the ASNS, CAD and FPGS were overexpressed in the prostate cancer group." (PMID 36983244, 2023).
ATCAY also shares sentences with these, for which no sentence is quoted: tumor (2 papers); cancer (1); Dengue (1); embryonic carcinoma (1); neuroaxonal dystrophy (1); neurological disorder (1); pheochromocytoma (1).